GRB10 (growth factor receptor bound protein 10)
Diseases named in the same sentence as GRB10 in open-access papers (continued):
Sharing a sentence is not in itself a finding about the gene and the disease.
depression (2 papers, 2022 to 2024). "We identified six core genes (GRB10, TDRD9, BCL7A, GPR18, KLRG1, and THEM4) significantly associated with depression and cancer." (PMID 39867577, 2024). "The results indicated that BCL7A (AUC: 0.656), GPR18 (AUC: 0.9677), GRB10 (AUC: 0.678), KLRG1 (AUC: 0.661), TDRD9 (AUC: 0.698), and THEM4 (AUC: 0.678) exhibit high diagnostic value for depression." (PMID 39867577, 2024). "To more accurately predict and assess the progression of depression, we constructed a nomogram model for depression diagnosis based on the core genes (GRB10, TDRD9, BCL7A, GPR18, KLRG1, and THEM4) using the rms package." (PMID 39867577, 2024). "This study conducted a comprehensive bioinformatics analysis, identifying six core genes (BCL7A, GPR18, GRB10, KLRG1, TDRD9, and THEM4) associated with depression and validating their diagnostic value in the context of the disorder." (PMID 39867577, 2024). "ROC analysis based on both GSE98793 and GSE76826 datasets suggested that S100A12, TIGIT, SERPINB2, GRB10, and LHFPL2 in the peripheral serum have the potential to act as diagnostic biomarkers for depression." (PMID 36325528, 2022). "No studies have reported a direct association of S100A12, TIGIT, SERPINB2, GRB10, and LHFPL2 with depression." (PMID 36325528, 2022). "The genes S100A12, TIGIT, SERPINB2, GRB10, and LHFPL2 in peripheral serum are viable diagnostic biomarkers for depression." (PMID 36325528, 2022). "Subsequently, S100A12, TIGIT, SERPINB2, GRB10, and LHFPL2 in peripheral blood were identified as Potential diagnostic biomarkers in peripheral blood for depression by SVM–REF, Random forest, and LASSO algorithms." (PMID 36325528, 2022). "S100A12, TIGIT, SERPINB2, GRB10, and LHFPL2 identified as potential diagnostic biomarkers in peripheral blood of patients with depression using three machine learning algorithms." (PMID 36325528, 2022). "In depression, GRB10 and TDRD9, involved in cell growth and stress responses, exhibited elevated expression, while BCL7A, GPR18, KLRG1, and THEM4, linked to immune regulation and apoptosis, showed reduced expression, suggesting dysregulated cellular signaling and impaired immune function." (PMID 39867577, 2024). "Based on the results of the ROC (validation set AUC value > 0.7) analysis in the current study, S100A12, TIGIT, SERPINB2, GRB10, and LHFPL2 may possess potential as diagnostic biomarkers of depression." (PMID 36325528, 2022). "For example, GRB10 and TDRD9, which are upregulated in depression, display variable expression patterns in different cancer types, reflecting their context-dependent roles." (PMID 39867577, 2024). "To investigate the correlation between cancer and depression, we examined the expression of BCL7A, GPR18, GRB10, KLRG1, TDRD9, and THEM4 across various cancer types using the TCGA database." (PMID 39867577, 2024). "qPCR results demonstrated that, compared to the normal control group, the expression of GRB10 and TDRD9 was significantly elevated in the blood of depression patients, while the expression of BCL7A, GPR18, KLRG1, and THEM4 was significantly reduced." (PMID 39867577, 2024). "We identified six core genes (BCL7A, GPR18, GRB10, KLRG1, TDRD9, and THEM4), confirming their critical value in diagnosing depression." (PMID 39867577, 2024). "Among them, GRB10 and TDRD9 were significantly upregulated, while BCL7A, GPR18, KLRG1, and THEM4 were significantly downregulated in patients with depression." (PMID 39867577, 2024). "We further investigated the role of S100A12, TIGIT, SERPINB2, GRB10, and LHFPL2 in depression and observed their expression profiles in patients." (PMID 36325528, 2022). "The expression level of 100A12, SERPINB2, GRB10, and LHFPL2 was higher in the depression group, whereas TIGIT showed a high expression profile in the normal control group." (PMID 36325528, 2022).
depression (continued). "Subsequently, the genes S100A12, SERPINB2, TIGIT, GRB10, and LHFPL2 in peripheral serum were identified as depression biomarkers by using machine learning algorithms." (PMID 36325528, 2022). "Among them, the relevance scores of S100A12, TIGIT, SERPINB2, GRB10, and LHFPL2 with depression were 4.356, 4.232, 3.064, 1.516, and 0.698, respectively." (PMID 36325528, 2022). "The results showed that the expression levels of GRB10 and TDRD9 were significantly increased in depression patients compared to the control group, while the expression levels of BCL7A, GPR18, KLRG1, and THEM4 were significantly decreased, all with statistical significance." (PMID 39867577, 2024). "Finally, the results from the three algorithms were combined, yielding S100A12, TIGIT, SERPINB2, GRB10, and LHFPL2 in peripheral blood as depression-related potential biomarkers." (PMID 36325528, 2022). "Initially, the correlation analysis showed that TIGIT had a significantly negative correlation with the level of SERPINB2 and GRB10 expression in patients with depression." (PMID 36325528, 2022). "These pathways indicate that GRB10 and TDRD9 are involved in critical cellular processes such as survival signaling, stress adaptation, and metabolic regulation, which may play central roles in the development and progression of depression." (PMID 39867577, 2024).
diabetic encephalopathy (2 papers, 2014 to 2016). A brain disease that is characterized by functional impairment of cognition, cerebral signal conduction, neurotransmission and synaptic plasticity, and underlying structural pathology associated with diabetes. "Based on these findings, we can speculate that, in diabetic encephalopathy, the effect of GIGYF2 on IGF1R signaling is not only mediated by cooperation with Grb10, but also by interaction with some other molecules." (PMID 25268761, 2014).
gastric cancer (2 papers, 2020 to 2023). A primary or metastatic malignant neoplasm involving the stomach. "Not only was the expression of GRB10 elevated in gastric cancer, but high expression of GRB10 was significantly associated with poorer overall prognosis survival." (PMID 37179120, 2023). "Especially in gastric cancer, the high GRB10 expression was closely associated with poorer overall survival." (PMID 37179120, 2023). "Overexpression of miR-379-5p in gastric cancer cells reduced GRB10-regulated gastric cancer proliferation and migration capacity." (PMID 37179120, 2023). "Further research showed that the knockdown of GRB10 inhibited proliferation and migration ability in gastric cancer." (PMID 37179120, 2023). "The results showed that the expression of GRB10 in gastric cancer tissues was significantly higher than that in adjacent tissues." (PMID 37179120, 2023). "In the follow-up work, more samples will be collected to analyze further the relationship between GRB10 expression and gastric cancer patients of different ethnicities." (PMID 37179120, 2023). "GRB10 expression was elevated in human gastric cancer cell lines AGS, SGC-7901 and BGC-803 compared with human gastric mucosal cell line GES1." (PMID 37179120, 2023). "Further studies revealed that the knockdown of GRB10 reduced the proliferation of gastric cancer cells." (PMID 37179120, 2023). "In this study, we found that the expression of GRB10 was elevated in gastric cancer using bioinformatics combined experiments in the present study." (PMID 37179120, 2023). "It showed that the expression of GRB10 was increased in the tumor tissue of gastric cancer patients." (PMID 37179120, 2023). "Only in gastric cancer, GRB10 expression was found to correlate with OS, progression free survival (PFI), disease free survival (DFI) and disease specific survival (DSS)." (PMID 37179120, 2023). "Knockdown of GRB10 significantly reduced the proliferation ability of gastric cancer cells, while overexpression of GRB10 increased the proliferation ability of gastric cancer cells." (PMID 37179120, 2023). "We used immunohistochemistry to evaluate the expression of GRB10 in collected 6 gastric cancer patients and paracancerous tissue specimens." (PMID 37179120, 2023). "In conclusion, in this study, it was revealed that the expression of GRB10 is closely related to the proliferation and migration ability of gastric cancer cells." (PMID 37179120, 2023). "Therefore, miR-379-5p and GRB10 were expected to be potential targets for the treatment of gastric cancer." (PMID 37179120, 2023). "Moreover, overexpression of GRB10 reduced the proliferation and migration ability of gastric cancer cells and restored the adhesion ability." (PMID 37179120, 2023). "In addition, the specific molecular mechanism of GRB10 regulating the proliferation and migration of gastric cancer is not fully understood, and further research is needed." (PMID 37179120, 2023). "However, the expression of GRB10 in gastric cancer and its role is still unclear." (PMID 37179120, 2023). "Therefore, we would focus on the relationship between the expression of GRB10 and gastric cancer." (PMID 37179120, 2023). "It was worth noting that in the human gastric cancer cell line AGS cell line, although the results of qRT-PCR showed that the expression of GRB10 was higher than that of GES1, the results of Western Blot did not." (PMID 37179120, 2023). "Statistical analysis showed that the TE, BAE, and MAE scores of imprinted genes GNAS, GRB10, and SNRPN were significantly increased in malignant samples for almost all ten cancer types (p < 0.01), with the only exception of SNRPN in gastric cancer." (PMID 32448196, 2020). "However, the relationship between the expression of GRB10 and the occurrence and development of gastric cancer has not been reported yet." (PMID 37179120, 2023). "As we noted in the Introduction, GRB10 has not been reported for gastric cancer." (PMID 37179120, 2023).
gastric cancer (continued). "However, whether miR-379-5p is involved in GRB10-mediated regulation of gastric cancer has not been elucidated." (PMID 37179120, 2023).
glioma (2 papers, 2020 to 2022). A benign or malignant brain and spinal cord tumor that arises from glial cells (astrocytes, oligodendrocytes, ependymal cells). "In addition, higher expression of GRB10 in glioma patients was associated with poorer clinical outcomes." (PMID 35790975, 2022). "The expression of GRB10 in glioma was determined based on the glioma transcriptome profile downloaded from The Cancer Genome Atlas (TCGA), Chinese Glioma Genome Atlas (CGGA), and Gene Expression Omnibus (GEO) databases." (PMID 35790975, 2022). "To further demonstrate the expression of GRB10 in glioma, we extracted the RNA from glioma, which was stored in the refrigerator at −80 °C." (PMID 35790975, 2022). "The expression of GRB10 was shown to be positively correlated with the histological grades of gliomas." (PMID 35790975, 2022). "Secondly, the RT-qPCR method was used to detect the expression of GRB10, more methods are needed to confirm the protein in glioma tissue." (PMID 35790975, 2022). "Further, we constructed GRB10 knockdown cell lines were constructed to investigate the effect of GRB10 on glioma." (PMID 35790975, 2022). "This study aimed to explore the function of growth factor receptor-bound protein 10(GRB 10) in glioma." (PMID 35790975, 2022). "Further, the study aims to conduct in vitro and in vivo assays to elucidate the functions of GRB10 in the development of glioma." (PMID 35790975, 2022). "Taken together, the expression of GRB10 was correlated to the OS of patients, suggesting that GRB10 performs a critical role in glioma progression." (PMID 35790975, 2022). "Taken together, the mRNA expression of GRB10 was positively correlated to the tumor grade, suggesting that GRB10 plays an oncogenic role in gliomas." (PMID 35790975, 2022). "RT-qPCR was performed to detect the expression of GRB10 in tissue samples obtained from 68 glioma patients." (PMID 35790975, 2022). "Using TCGA analysis, we demonstrated that Grb10 was highly expressed in more aggressive glioma tumors and its expression was directly correlated with worse prognosis." (PMID 33093452, 2020). "Using TCGA we analyzed the expression of Grb10 in various subtypes of glioma and found that the expression of Grb10 was significantly higher in GBM compared with low-grade tumors as determined by histology criteria and the WHO grade." (PMID 33093452, 2020). "Our data revealed that GRB10 regulated tumorigenesis in glioma and played a vital role in promoting the glioma progression, which indicated that GRB10 could be used as a potential prognostic marker." (PMID 35790975, 2022). "Moreover, the expression of GRB10 was negatively correlated to the clinical outcomes of glioma patients." (PMID 35790975, 2022). "It is further speculated that GRB10 may promote the progression of glioma by affecting the hypoxia and EMT pathways, but the specific mechanism needs to be further studied." (PMID 35790975, 2022). "In this study, it was confirmed that GRB10 plays an oncogene role in glioma." (PMID 35790975, 2022). "This study revealed that high expression of GRB10 could promote tumor formation and progression in gliomas." (PMID 35790975, 2022). "The expression level of GRB10 was positively correlated to the histological grades of gliomas." (PMID 35790975, 2022). "In addition, Kaplan-Meier survival curves revealed that glioma patients with lower expression of GRB10 had more prolonged survival." (PMID 35790975, 2022). "For example, the mRNA of GRB10 was highly expressed in grade IV gliomas." (PMID 35790975, 2022). "The mRNA expression level of GRB10 was evaluated in 68 patients with different grades of gliomas." (PMID 35790975, 2022). "The results revealed that GRB10 promoted in vivo and in vitro cell growth in glioma." (PMID 35790975, 2022). "In addition, analysis of methylation glioma subtypes demonstrated that Grb10 was highly expressed in the mesenchymal subtype and exhibited lowest expression in the G-CIMP high tumors." (PMID 33093452, 2020).
glioma (continued). "However, there were no studies that explored the relationship between GRB10 and cell proliferation in gliomas." (PMID 35790975, 2022). "However, the role of GRB10 and GRB14 in glioma has not been fully elucidated." (PMID 35790975, 2022).
Hyperglycemia (2 papers, 2016 to 2023). An increased concentration of glucose in the blood. "In conclusion, our data indicates that continuous hyperglycemia might lead to an elevated expression of Grb10 and the subsequent decrease in IGF-1/IGF-1R signaling in kidneys, which may consequently contribute to the pathogenesis of diabetic nephropathy." (PMID 26986757, 2016).
insulinoma (2 papers, 2014 to 2024). "The growth factor receptor-bound protein 10 (GRB10), a negative regulator of insulin and mTORC1 signaling, is significantly elevated in the islets of diabetic mice and insulinoma cells treated with high glucose." (PMID 39057094, 2024). "To gain insight into the mechanisms by which GRB10 influences pancreatic β- and α-cell function, we disrupted Grb10 expression in rat insulinoma INS-1 cells by siRNA and in human islets by shRNA achieved by lentiviral transfection." (PMID 24699409, 2014). "While Grb10 knock-down in the rat insulinoma cell line INS-1 lacking glucagon resulted in marked reduction of insulin, GRB10 knock-down in human pancreatic islets resulted in reduction in both insulin and glucagon secretion and expression." (PMID 24699409, 2014).
melanoma (2 papers, 2016 to 2024). A malignant, usually aggressive tumor composed of atypical, neoplastic melanocytes. "MiR-222/221 directly targets growth factor receptor-bound protein 10 (GRB10) and estrogen receptor-alpha (ESR1), which participate in promoting melanoma invasion." (PMID 39201498, 2024).
neuroblastoma (2 papers, 2015 to 2022). Neuroblastoma (NB) is the most common solid, extracranial childhood tumor. "Patient samples from 4 neuroblastoma cohorts had HuD RNA levels significantly correlate with GRB-10 and ARL6IP1 RNA levels." (PMID 35012594, 2022). "In summary, we identified HuD as binding and stabilizing two RNA substrates, GRB-10 and ARL6IP1, in neuroblastoma cells and mapped its relevant binding domains." (PMID 35012594, 2022). "Growth factor receptor-bound protein 10 (GRB10) IHC revealed high levels of localization in non-metastatic neuroblastoma tissues." (PMID 26148557, 2015).
osteosarcoma (2 papers, 2023 to 2025). A usually aggressive malignant bone-forming mesenchymal neoplasm, predominantly affecting adolescents and young adults. "GRB10 has been associated with osteosarcoma in Irish Wolfhounds and has also been linked to osteosarcoma in humans." (PMID 41012800, 2025). "Functionally, RILP inhibits proliferation, migration, invasion, and promotes autophagy in osteosarcoma cells via Grb10-mediated inhibition of the PI3K/AKT/mTOR signaling pathway." (PMID 37789274, 2023). "Functional experiments suggested that downregulation of Grb10 attenuated the inhibition effect of RILP on osteosarcoma cell proliferation, migration, and invasion, the opposite is true for Grb10 overexpression." (PMID 37789274, 2023). "In conclude, RILP restrains osteosarcoma progression via Grb10-mediated inhibition of the PI3K/AKT/mTOR pathway." (PMID 37789274, 2023). "Our study revealed that the expression of RILP was associated with favorable prognosis of osteosarcoma and RILP inhibits proliferation, migration, and invasion and promotes autophagy in osteosarcoma cells via Grb10-mediated inhibition of the PI3K/AKT/mTOR signaling pathway." (PMID 37789274, 2023). "Co-immunoprecipitation assay in 143B osteosarcoma cells showed that RILP interacted with Grb10." (PMID 37789274, 2023). "In this study, we observed that RILP could interact with Grb10 and promote its phosphorylation, thus affecting the malignant phenotypes of osteosarcoma." (PMID 37789274, 2023). "However, the specific role of Grb10 in osteosarcoma remains nebulous." (PMID 37789274, 2023). "Our results identified that RILP could bind to Grb10 and participate in the inhibition of the PI3K signaling pathway, thus affecting the progression of osteosarcoma." (PMID 37789274, 2023). "Since Grb10 is involved in negative regulation of the PI3K/AKT signaling pathway, we hypothesized that RILP could interact with Grb10 to inhibit the PI3K signaling pathway, ultimately affecting the osteosarcoma phenotype." (PMID 37789274, 2023).
Prader-Willi syndrome (2 papers, 2015 to 2022). "Thus, the Ddc-Grb10 imprinted gene cluster may have evolved important parental controls over decision making along with the multiple imprinted genes involved in Prader-Willi syndrome." (PMID 35263575, 2022).